CASC2 (cancer susceptibility 2)
Diseases named in the same sentence as CASC2 in open-access papers (continued):
Sharing a sentence is not in itself a finding about the gene and the disease.
lung adenocarcinoma (3 papers, 2018 to 2022). A carcinoma that arises from the lung and is characterized by the presence of malignant glandular epithelial cells. "It has been reported that CASC2 can inhibit the progression of lung adenocarcinoma and is associated with drug resistance in cancer patients." (PMID 35665444, 2022). "The downregulation of CASC2 has been demonstrated to promote lung adenocarcinoma and shows a negative correlation with the development of drug resistance of the tumor patients." (PMID 35665444, 2022).
nephritis (3 papers, 2023 to 2024). Inflammation of renal tissue. "Among them, the level of urinary cancer susceptibility candidate 2 (CASC2) can evaluate the histological grade of nephritis, which may be the highest in patients with simple grade V nephritis." (PMID 39364719, 2024). "In this study, we found that urinary CASC2 levels were significantly different between different histological classes of lupus nephritis, and pure class V nephritis had the highest levels." (PMID 37511572, 2023). "When the lupus nephritis group was further analyzed, it was found that there was a significant difference in urinary CASC2 levels between histological classes of nephritis (Kruskal–Wallis test, p = 0.026), and patients with pure class V nephritis probably had the highest levels." (PMID 37511572, 2023). "As a result, this research was designed to investigate lncRNA CASC2 and miR-155 levels as non-invasive diagnostic biomarkers in SLE patients, including those with and without nephritis, and to investigate their effectiveness in assessing disease severity and predicting LN." (PMID 39690146, 2024).
renal cell carcinoma (3 papers, 2017 to 2020). "In RCC (renal cell carcinoma) (n = 32), CASC2 was significantly downregulated compared with the matched normal tissue." (PMID 33120918, 2020).
asthma (2 papers, 2020 to 2022). "For instance, the expression of lncRNA CASC2 in serum was at a lower level in asthma children than healthy individuals, which suggested that lncRNA CASC2 might be involved in childhood asthma." (PMID 35656293, 2022). "This study constructed an asthma-associated competing endogenous RNA network, determined 5 key long non-coding RNAs (MALAT1, MIR17HG, CASC2, MAGI2-AS3, DAPK1-IT1) and identified 8 potential new drugs (Tamoxifen, Ruxolitinib, Tretinoin, Quercetin, Dasatinib, Levocarnitine, Niflumic Acid, Glyburide)." (PMID 31924195, 2020). "Then by utilizing bioinformatics tools, we constructed a lncRNA-miRNA-mRNA ceRNA network, from which we extracted asthma related DE ceRNA network and recognized 5 potential key lncRNAs (MALAT1, MIR17HG, CASC2, MAGI2-AS3 and DAPK1-IT1)." (PMID 31924195, 2020). "We then constructed a lncRNA-miRNA-mRNA global ceRNA network and extracted asthma-related DE ceRNA network, from which we determined 5 key lncRNAs (MALAT1, MIR17HG, CASC2, MAGI2-AS3, DAPK1-IT1)." (PMID 31924195, 2020). "Even though CASC2, MAGI2-AS3, and DAPK1-IT1 had fewer results, they were also enriched in many asthma-related functions and pathways, as “cytokine production involved in immune response”, “mesenchymal cell proliferation”, “phosphatidylinositol 3-kinase activity”, etc." (PMID 31924195, 2020). "No study had assessed lncRNA MALAT1, MIR17HG, CASC2, MAGI2-AS3 and DAPK1-IT1 in asthma." (PMID 31924195, 2020).
childhood asthma (2 papers, 2022). "CASC2 is involved in childhood asthma through inhibiting ASMCs proliferation, migration, and inflammation via miR-31-5p activity." (PMID 36612051, 2022). "For instance, lncRNA CASC2 and BAZ2B are increased in the serum of childhood asthma." (PMID 36612051, 2022).
kidney failure (2 papers, 2021 to 2022). An acute or chronic condition that is characterized by the inability of the kidneys to adequately filter the blood. "Low serum level of CASC2 was associated with higher incidence of kidney failure, indicating that serum lncRNA CASC2 could be a biomarker for prediction of the occurrence of kidney failure in type 2 DM patients." (PMID 36313695, 2022).
lupus (2 papers, 2023 to 2024). "Urinary CASC2 level did not correlate with any parameters of lupus activity." (PMID 37511572, 2023).
lymph node metastasis (2 papers, 2019 to 2023). "Furthermore, univariate analyses showed that CASC2 expression, TNM stage, and lymph node metastasis were significantly associated with OS and DFS." (PMID 36816357, 2023). "We found that CASC2 levels were significantly associated with tumor differentiation, lymph node metastasis, and TNM stage, but not correlated with age, gender, tumor size, smoking status and tumor location." (PMID 31728180, 2019).
papillary thyroid cancer (2 papers, 2020 to 2022). "Long noncoding RNA cancer susceptibility candidate 2 (CASC2) has been reported to play an anticancer role in papillary thyroid cancer (PTC)." (PMID 33134385, 2020).
pulmonary hypertension (2 papers, 2019 to 2020). Increased pressure within the pulmonary circulation due to lung or heart disorder. "LncRNA cancer susceptibility candidate 2 (CASC2) has been revealed to be involved in PASMC injury in hypoxia-induced pulmonary hypertension." (PMID 32206065, 2020). "In this study, we aimed to investigate whether and how lncRNA CASC2 was involved in hypoxia-induced pulmonary hypertension (PH)-related vascular remodeling." (PMID 30857524, 2019).
type 2 diabetes (2 papers, 2020 to 2023). "CASC2 in serum and renal tissue was specifically downregulated in patients with type 2 diabetes with podocyte injury, and CASC2 upregulation suppressed proliferation, the accumulation of extracellular matrices, and oxidative stress in mesangial cells through the miR-133b/FOXP1 regulatory axis." (PMID 37511572, 2023).
ulcer (2 papers, 2022 to 2025). "A research team analyzed the expression of lncRNA cancer susceptibility candidate 2 (CASC2) in ulcer tissue from both human patients and mice." (PMID 40861221, 2025). "Our research showed the lower level of lncRNA CASC2 in the ulcer marginal tissues of DFU patients and mice and the higher level of miR-155 in DFU patients." (PMID 35845734, 2022). "We have analyzed lncRNA CASC2`s expression in the marginal tissues of ulcers in patients and mice with DFU." (PMID 35845734, 2022). "According to our study, the lncRNA CASC2's expression was low in the tissues of ulcers of DFU mice and patients." (PMID 35845734, 2022).
acute respiratory distress syndrome (1 paper, 2021). Progressive and life-threatening pulmonary distress in the absence of an underlying pulmonary condition, usually following major trauma or surgery. "For example, MALAT1 was reportedly related to acute respiratory distress syndrome related to lung injury, downregulation of SNHG14 had protective effects against LPS-induced ALI, and CASC2 improved ALI by reducing lung epithelial cell apoptosis." (PMID 33506021, 2021).
astrocytomas (1 paper, 2020). "In support of this, the RT-qPCR analysis showed that miR-21 expression is moderately upregulated in low-grade astrocytoma and even highly upregulated in malignant glioblastoma, while high expression of CASC2 in tumors might be responsible for the decrease of miR-21 expression." (PMID 33120918, 2020).
breast tumor (1 paper, 2023). "Additionally, the level of lncRNAs NEAT1, CASC2, and LINC00299 in breast tumor tissues increased significantly by twofold, 1.5‐fold, and 2.3‐fold, respectively, compared to adjacent nonmalignant samples (p < 0.05)." (PMID 37706018, 2023).
bronchopulmonary dysplasia (1 paper, 2022). Bronchopulmonary dysplasia is a chronic respiratory disease that results from complications related to lung injury during the treatment of infant acute respiratory distress syndrome in low-birth-weight premature infants or from abnormal lung development in older infants. "It was also shown that overexpression of CASC2 can alleviate lung damage in newborns caused by bronchopulmonary dysplasia." (PMID 35665444, 2022). "In addition, CASC2 is also involved in the regulation of LPS‐induced lung injury; overexpression of CASC2 can attenuate lung damage in newborns caused by bronchopulmonary dysplasia." (PMID 35665444, 2022).
cardiac hypertrophy (1 paper, 2020). "Cardiac hypertrophy is associated with alterations in calcium handling and hence, it is reassuring that genes encoding for proteins involved in calcium handling and signaling (CACNA1D, CACNA1G, CACNA1S or CASC2) also show differential expression at all time points in our model." (PMID 32878883, 2020).
cholangiocarcinoma (1 paper, 2024). A carcinoma that arises from the intrahepatic biliary tree (intrahepatic cholangiocarcinoma) or from the junction, or adjacent to the junction, of the right and left hepatic ducts (hilar cholangiocarcinoma). "However, the integration of our data with existing literature on the CASC2/miR-18a/SOCS5 axis provides a deeper understanding of the molecular mechanisms underpinning cholangiocarcinoma and highlights potential avenues for therapeutic intervention." (PMID 39458127, 2024).
COVID-19 (1 paper, 2024). A disease caused by infection with severe acute respiratory syndrome coronavirus 2. "In our study, we revealed the expression profile of lncRNA CASC2 and miRNA-21-5p in cases with COVID-19 and explored their association with each other and with the clinicopathological manifestations of patients." (PMID 38342902, 2024). "We demonstrated for the first time that lncRNA CASC2 is downregulated in the serum of COVID-19 patients, which is probably protective against SARS-CoV-2 infection." (PMID 38342902, 2024). "Results detected that CASC2 was significantly downregulated while miRNA-21-5p was significantly upregulated in COVID-19 patients compared to healthy subjects." (PMID 38342902, 2024). "We reported that lncRNA CASC2 was significantly downregulated in COVID-19 patients than in healthy controls." (PMID 38342902, 2024). "ROC curve showed that CASC2 can discriminate COVID-19 patients from healthy people (AUC = 0.784, 95% CI (0.674–0.895), p < 0.001) with a sensitivity of 76.5% and a specificity of 100% at a cutoff > 0.987 (fold)." (PMID 38342902, 2024). "The present study aimed to identify the expression levels of lncRNA CASC2 and miRNA-21-5p (also known as miRNA-21) in COVID-19 patients and their relation to the clinicopathological characteristics of the disease." (PMID 38342902, 2024). "According to our research, patients with COVID-19 may benefit from the therapeutic use of the lncRNA CASC2." (PMID 38342902, 2024). "Consequently, the purpose of this study aimed to investigate for the first time the involvement of lncRNA CASC2 in COVID-19." (PMID 38342902, 2024). "Furthermore, a strikingly negative correlation between CASC2 and miRNA-21-5p expression levels in the serum of COVID-19 patients was observed." (PMID 38342902, 2024).
diabetes (1 paper, 2022). "Previous studies have found that CASC2 is involved in the pathological process of regulating diabetes and its complications." (PMID 35845734, 2022).
epilepsy (1 paper, 2021). A brain disorder characterized by episodes of abnormally increased neuronal discharge resulting in transient episodes of sensory or motor neurological dysfunction, or psychic dysfunction. "Increased CASC2 can also repress epilepsy seizures in epileptic rats." (PMID 34675776, 2021). "Elevated CASC2 hinders astrocyte activation and restrains astrocyte adenosine metabolism via triggering phosphatase and tensin homolog (PTEN) expression during epilepsy." (PMID 34675776, 2021).
ischaemic stroke (1 paper, 2022). "After matching ischaemic stroke-related lncRNAs with berberine-related lncRNAs, four genes (H19, HOTAIR, CASC2, and LINC00943) were selected as potential targets for berberine in the treatment of ischaemic stroke." (PMID 35815278, 2022).
liver neoplasm (1 paper, 2021). Tumors or cancers of the LIVER. "Given that RIPK1 was significantly downregulated in Huh-7 (R) and HCCLM3 (R) cells, next, ENCORI and TargetScan 7.2 were used to analyze miRNAs that might bind to CASC2 and RIPK1; moreover, HMDD v3.2 data were used to analyze miRNAs that might relate to liver neoplasms." (PMID 35145900, 2021).
lung diseases (1 paper, 2022). "LncRNA CASC2 is closely related to the occurrence and development of various human lung diseases." (PMID 35665444, 2022).
lupus nephritis (1 paper, 2023). Glomerulonephritis in the context of systemic lupus erythematosus. "With ROC curve analysis, the AUC of MALAT and CASC2 for the identification of lupus nephritis was 0.985 and 0.905, respectively (p < 0.0001 for both)." (PMID 37511572, 2023). "In the second study, urinary levels of the lncRNA targets MALAT and CASC2 were quantified in 78 lupus nephritis patients with various histological classes, as well as seven healthy controls." (PMID 37511572, 2023). "As a whole group, urinary MALAT1 and CASC2 levels were significantly increased in lupus nephritis compared to healthy controls (31.3 [IQR 21.5–61.9] vs. 9.3 [IQR 9.2–11.5] copies and 18.4 [IQR12.2–156.0] vs. 9.9 [IQR 9.7–12.1] copies, respectively; p < 0.0001 for both)." (PMID 37511572, 2023). "The characteristics of CASC2 and MALAT1 suggest that they may affect the phenotype (i.e., histological class) of lupus nephritis." (PMID 37511572, 2023).
ovarian tumor (1 paper, 2021). "However, downregulation of EIF4A3 reversed the effect of CASC2 reduction when combined with sanguinarine in ovarian tumor cells, while it also reversed the effect of CASC2 on the NF-κB and PI3K/AKT/mTOR pathways." (PMID 34458150, 2021).
pneumonia (1 paper, 2022). An acute, acute and chronic, or chronic inflammation focally or diffusely affecting the lung parenchyma, caused by an infection in one or both of the lungs (by bacteria, viruses, fungi, or mycoplasma.). "The ROC curve indicated the diagnostic value of CASC2 for severe pneumonia from healthy people with the ROC of 0.912; the sensitivity and specificity were 93.3% and 80.6%, respectively." (PMID 35665444, 2022). "This study tested the expression pattern of long noncoding RNA cancer susceptibility candidate 2 (CASC2) in the serum of children with severe pneumonia and explored its clinical values." (PMID 35665444, 2022). "According to the mean value of serum CASC2 in all children with severe pneumonia, all cases were divided into low CASC2 group (n = 79) and high CASC2 group (n = 66)." (PMID 35665444, 2022). "The serum levels of CASC2 significantly decreased in children with severe pneumonia in contrast with healthy individuals and reached the lowest value in those with RF." (PMID 35665444, 2022). "In the current study, a reduction of serum CASC2 was detected in the serum of children with severe pneumonia in comparison with healthy individuals." (PMID 35665444, 2022). "The serum levels of CASC2 significantly decreased in children with severe pneumonia in contrast with healthy individuals (P < 0.001) and reached the lowest value in children with RF (P < 0.001)." (PMID 35665444, 2022). "Attention should be paid to the changes of serum CASC2 levels in children with severe pneumonia complicated with RF, and timely intervention should be taken to improve the prognosis." (PMID 35665444, 2022). "In the current study, nearly 20% of cases died from severe pneumonia during the 28‐day follow‐up, and they had low levels of serum CASC2." (PMID 35665444, 2022). "Herein, we detected the expression pattern of CASC2 in the serum of children with severe pneumonia and explored its clinical values." (PMID 35665444, 2022). "Based on the serum levels of CASC2 in healthy individuals and children with severe pneumonia, the ROC curve was established." (PMID 35665444, 2022). "The findings reflected that serum CASC2 was related to the RF progression of children with severe pneumonia." (PMID 35665444, 2022). "The close association supported our speculation about the important role of CASC2 in the clinical outcome of children with severe pneumonia." (PMID 35665444, 2022). "In conclusion, downregulation of serum CASC2 was related to the occurrence of RF in children with severe pneumonia and may be a predictor of clinical outcomes." (PMID 35665444, 2022). "Furthermore, the K‐M plot indicated that cases with low CASC2 levels had a poor survival rate, and CASC2 can independently influence the survival rate of children with severe pneumonia." (PMID 35665444, 2022). "Serum CASC2 can distinguish severe pneumonia and predicted the development of RF." (PMID 35665444, 2022). "Serum levels of CASC2 were detected in 145 children with severe pneumonia." (PMID 35665444, 2022). "CASC2 (hazard ratio [HR] = 0.068, 95% confidence interval [CI] = 0.016–0.292, P < 0.001) and age (HR = 2.806, 95% CI = 1.240–6.394, P < 0.001) were independent influence factor for the poor prognosis of children with severe pneumonia." (PMID 35665444, 2022). "Serum levels of CASC2 significantly decreased in children with severe pneumonia." (PMID 35665444, 2022). "Serum CASC2 can distinguish severe pneumonia, and predicted the development of respiratory failure." (PMID 35665444, 2022). "Downregulation of serum CASC2 was related to the occurrence of RF in children with severe pneumonia and may be a predictor of the poor prognosis." (PMID 35665444, 2022). "But the predicting role of CASC2 in pneumonia should be confirmed in another population." (PMID 35665444, 2022). "In the current study, we focus on the mRNA pattern of CASC2 in pneumonia patients; its genotype data at the gene level was not included." (PMID 35665444, 2022).
pneumonia (continued). "In addition, measurement of CASC2 in the children who had pneumonia after they had recovered was not included, which should be elucidated in future study." (PMID 35665444, 2022). "Interestingly, decreased CASC2 levels showed a negative correlation with the levels of CRP, IL‐6, PCT, and D‐dimer in children with severe pneumonia." (PMID 35665444, 2022).
Right ventricular hypertrophy (1 paper, 2019). In this case the right ventricle is more muscular than normal, causing a characteristic boot-shaped (coeur-en-sabot) appearance as seen on anterior- posterior chest x-rays. "In short, lncRNA CASC2 suppressed progression of right ventricular hypertrophy caused by hypoxia in rat pulmonary arterial tissues." (PMID 30857524, 2019). "Besides, up-regulation of mPAP and RVI caused by Hypoxia was partly attenuated by overexpression of lncRNA CASC2 in Hypoxia + p-CASC2 group compared with normoxia group, indicating suppressive role of lncRNA CASC2 in progression of right ventricular hypertrophy." (PMID 30857524, 2019).